IL5 (interleukin 5)
Diseases named in the same sentence as IL5 in open-access papers (continued):
Sharing a sentence is not in itself a finding about the gene and the disease.
eosinophilia (continued). "In view of that, leukotriene - ILC2 pathway in respiratory diseases (which level of CysLTs increase) might promote airway eosinophilia inflammation and hyper responsiveness by enhancing production of IL4, IL5 and IL13 Fig.." (PMID 28761563, 2017). "IL-5 is a critical factor for eosinophil production and activation, but animal model showed that CD2-IL-5 Tg induced eosinophilia in blood, not in tissue." (PMID 29029406, 2017). "It was reported that oxymatrine and taraxasterol could reduce the production of IL-4, IL-5, and IL-13 in bronchoalveolar lavage fluid and OVA-specific IgE in sera and inhibit OVA-induced eosinophilia in lung tissues." (PMID 28751921, 2017). "Monoclonal antibodies to IL-5 or its receptor, and CRTH2 antagonists, both of which may help to ameliorate the persistent steroid resistant eosinophilia and elevated Th2 and ILC2 cells that are apparent." (PMID 28725641, 2017). "The underlying mechanism for this effect is unclear, as the reduction in eosinophilia was not correlated with a decrease in IL-5, CCL11, or CCL24, and eosinophil migration itself was not inhibited by IL-2c." (PMID 29196657, 2017). "In KSpn-mediated suppression of AAD we identified important suppressive roles for: TLR2 in eosinophil infiltration into the airways (partial) and AHR; TLR4 in eosinophilia of the airways and blood, IL-5 and IL-13 release from splenocytes and AHR, and; MyD88 in airway and blood eosinophilia and AHR." (PMID 27309732, 2016). "In the absence of TLR2, MLN T cell and splenocyte release of IL-5 were reduced but there was no impact on eosinophilia in the BALF or blood." (PMID 27309732, 2016). "Together, these reports suggest that ILC2-derived IL-5 and IL-13 contribute nonredundantly to eosinophilia." (PMID 26965110, 2016). "Then in AAD we identified inductive roles for: TLR2 in IL-5 release from MLN T cells, IL-5 and IL-13 release from splenocytes and AHR; TLR4 in eosinophil infiltration into BALF and blood (partial) and AHR, and; MyD88 in blood eosinophilia, IL-13 release from MLN T cells and AHR." (PMID 27309732, 2016). "It has been reported that murine model which is in lack of IL-5 expression would not develop AHR or eosinophilia though under allergen challenge." (PMID 26035827, 2015). "Moreover, pICLC treated mice displayed diminished GATA3+ IL-5 producing CD4 T cells and dramatically reduced eosinophilia, but increased RORγt+ IL-17A producing CD4 T cells." (PMID 26252005, 2015). "In this study, our protocol was shown to mimic prototypical characteristics of clinical atopic asthma, namely blood, tissue and BALF eosinophilia, an elevation of TH2 cytokines IL-5 and IL-13 in BALF, and prominent AHR, as shown by a heightened reactivity to methacholine." (PMID 25089623, 2014). "TLR4-deficient mice challenged with either OVA preparation showed eosinophilia but not neutrophilia and had increased IL-5." (PMID 24968337, 2014). "RAG−/− mice, either with or without Anakinra treatment, also failed to generate granulomas in response to Hp larval invasion (data not shown), despite exhibiting increased IL-5 levels and increased peritoneal eosinophilia." (PMID 23935505, 2013). "Further, IL-25 administered to RAG1 knockout mice that lack B or T cells led to eosinophilia and increased tissue IL-5 and IL-13 expression suggesting that a non-B/non-T cell population was active in vivo." (PMID 24876829, 2013). "In contrast, anti-IL-5 treatment prevented H. polygyrus-induced eosinophilia, whereas it did not alter the parasite loads." (PMID 22360486, 2012). "Taken together, we speculate that inhibition of NF-κB activation directly or indirectly attenuated IL-5, IL-13, eotaxin, RANTES, TNF-α, and TGF-β gene expression, eosinophilia infiltration, mucus production, collagen deposition, and allergic lung inflammation." (PMID 22675381, 2012). "In humans, the concentrations of eotaxin-2, IL-5, IL-10 and TNF-α are correlated with eosinophilia." (PMID 22360486, 2012).
eosinophilia (continued). "This is supported experimentally, whereby IL-5−/− mice, which have significantly reduced allergen-induced airway eosinophilia, are protected from TGF-β dependent remodelling, and clinically following anti-IL-5 treatment in asthmatic patients which reduced ECM deposition." (PMID 19769993, 2010). "Moreover, the two cell populations were broadly similar in reduction of IL-5 and eotaxin in the BALF, consistent with the attenuated degree of eosinophilia." (PMID 20306466, 2010). "The mechanisms behind the pulmonary manifestations may be similar, and due to the occurrence of eosinophilia and pulmonary infiltrations, suggest the role for cytokines such as tumor necrosis factor alpha (TNF-α), interleukin-5 (IL-5) and chemokines." (PMID 16756657, 2006). "The third patient may have had eosinophilia that was not IL-5 independent or could have been producing excessive IL-5 that outpaced the effectiveness of mepolizumab injections." (PMID 41322417, 2025). "The absence of a pronounced effect of BNC on the levels of IL-4, responsible for the activation of B-lymphocytes and humoral immunity, and IL-5, which stimulates eosinophilia, is consistent with the lack of allergenic effect of BNC in the model of systemic anaphylaxis." (PMID 39453014, 2024). "(ii)The clonal nature of eosinophilia is not established, as eosinophilia may be secondary to the production of eosinophilopoietins, such as IL-5, by one or more clonal cells other than eosinophils." (PMID 37122022, 2023). "Although most of the eosinophilia is transient and does not develop clinical symptoms, treatment with prednisolone or dual therapy with anti-IL-5/5R monoclonal antibody may be needed in some cases." (PMID 36362100, 2022). "Second, patients treated with anti-IL5 monoclonal antibodies who have suboptimal treatment responses may continue to have persistent airway eosinophilia, which is not reflected by blood eosinophil counts." (PMID 36237537, 2022). "In comparison, trehalose did not affect LPS‐mediated upregulation of CD69 on mouse blood eosinophils and mRNA levels of IL‐5 and IL‐13 in human eosinophilic cell line, suggesting that trehalose may not directly act on eosinophils to alleviate eosinophilia." (PMID 35988262, 2022). "Eosinophilia was sharply reduced by Hp‐TGM co‐administration, indicating direct effect(s) on innate cell populations, together with overall diminution of type 2 cytokines, in particular BALF IL‐5 and lung IL‐33, the latter known to be an essential driver of immune responses in this model." (PMID 35758054, 2022). "Furthermore, IL‐5 and IL‐13 are important CD4 T‐cells and ILC2‐derived cytokines that are involved in eosinophilia, mucus production, and airway hyperreactivity, and they have been suggested as biomarkers and therapeutic targets for type‐2 inflammation‐related disorders such as allergic asthma." (PMID 34873877, 2022). "It is clinically important to underline that eotaxin-1 cannot mobilize eosinophils without synergia with IL-5, meaning that blocking IL-5 is far more crucial treatment-wise, since eotaxin-1 alone can only lead to blood eosinophilia but not to tissue infiltration." (PMID 33921360, 2021). "For example, ILC2s, potent sources of IL-5, IL-9, IL-13, and PGD2, have been found to be higher in blood and sputum of severe asthmatics on high-dose steroids compared to mild asthmatics, and that these numbers are even higher in those with uncontrolled eosinophilia despite OCS." (PMID 35126131, 2021). "The increased adult worm burden at a late time point of infection in animals lacking eosinophilia (IL-5−/−, IL-4R−/−/IL-5−/−, dblGATA) further suggests that the extended microfilaremia is rather due to this prolonged adult worm survival than an impaired MF clearance." (PMID 31109364, 2019).
eosinophilia (continued). "A similar result has been observed in experimental allergic asthma, where the transfer of CCR4+ regulatory T cells obtained from spleens and lymph nodes, but not CCR4− regulatory T cells, attenuates eosinophilia, the production of IL-4 and IL-5, and airway inflammation." (PMID 30584243, 2018). "In addition, inhalation of heat-inactivated FAP did not induce airway eosinophilia accompanied by eosinophilia or elevation of IL-5 in the BAL fluids." (PMID 30575775, 2018). "It has been suggested that lower doses of anti-IL-5 drugs might not neutralize completely IL-5, which could still be able to promote local airway eosinophilia, in spite of the normalization of the blood eosinophil count." (PMID 30498762, 2018). "Finally, the HPC count as well as ST2 and intracellular IL-5 expression by these cells were measured in the patients with sputum eosinophilia and in those without." (PMID 29859068, 2018). "This review may help identify targets that are upstream of GM-CSF and downstream of IL-3 to supplement anti-IL-5 therapies, which despite their efficacy, have not totally controlled eosinophilia and EOS-related pathology." (PMID 28971096, 2017). "High levels of IL-5 and the resultant eosinophilia are protective against some parasite species, but not against others and may even be counterproductive." (PMID 29163523, 2017). "Additionally, older studies have demonstrated that anti-IL-5 therapy reduced eosinophilia but not AHR and the LAR in humans." (PMID 25450500, 2015). "In addition, we also evaluate for hyperplastic chronic rhinosinusitis and non-IgE mediated eosinophilia possibly mediated by antigen-triggered IL-5 release from T-lymphocytes." (PMID 21362188, 2011). "Interestingly, we measured substantial increases in IL-4, IL-5, IL-13, and IL-17 from restimulated CD4+ T cells as well as substantial increases in eosinophilia and neutrophilia in the BAL, indicating that our one sensitization model polarizes CD4+ T cells down both Th2 and Th17 pathways." (PMID 20659336, 2010). "The fact that total Mf production is higher with IL-5 than without IL-5 could reflect the parasite having optimized to an environment with high immunity and using IL-5–induced eosinophilia as a signal for reproduction." (PMID 20976100, 2010). "Interestingly, when systemically administered to mice, IL-25 induces IL-4, IL-5 and IL-13 production from undefined non-T/non-B cells and then induces Th2-type immune responses such as blood eosinophilia and increased serum immunoglobulin E levels." (PMID 18315837, 2008). "Importantly for the development of asthmatic symptoms, the activation of inflammatory Th2 cells through TSLP and their production of the inflammatory cytokines IL-4, IL-5, IL-13 and TNF-α triggers IgE production, eosinophilia, mucus production and fibroblast proliferation." (PMID 18724870, 2008). "The finding that not only transfer of CD3IL-5+ CD8+ T lymphocytes but also transfer of CD8+ T lymphocytes from C57BL/6 mice restore BM eosinophilia in immunodeficient mice further argues that the role of CD8+ T lymphocytes in BM eosinophilopoiesis is independent of IL-5 overproduction." (PMID 16740158, 2006). "We may also conclude that when eosinophils have already migrated to the lungs, TRFK-5 has no power to inhibit eosinophilia, which is also under control of local lung cells producing IL-5." (PMID 18475693, 1996). "Although the pathophysiology is not entirely clear, the potential hypothesis behind eosinophilia can be explained by the excessive secretion of catecholamines, IL-5, and other cytokines that are responsible for eosinophil differentiation, activation, and survival." (PMID 41477390, 2025). "The striking similarities between treatment with mepolizumab and the situation in IL-5-KO mice support the hypothesis that mepolizumab is particularly antagonizing reactive eosinophilia rather than blocking the maturation of the complete eosinophil compartment." (PMID 34409272, 2021).
eosinophilia (continued). "Our study could not find a significant correlation between IL-5 and eosinophilia." (PMID 27882241, 2016). "IL-5 may not be the sole determinants of persistent airway eosinophilia." (PMID 25709744, 2014). "Because of its restriction to the eosinophil/basophil lineage in humans, IL-5 therapy may attenuate key characteristics of allergic airway inflammation, such as airway eosinophilia, airway remodeling, and AHR, without affecting the function of other immune cells." (PMID 24032029, 2013). "We further observed an early increase in dual production of IL-5 and IL-17A in ST2+ ILCs followed by enhanced lung eosinophilia in the absence of IL-18R." (PMID 40777291, 2025). "Immunohistochemical analysis of TARC and IL-5 has demonstrated higher expression in PTCL-NOS and NTFHL-AI cases with eosinophilia compared to those without." (PMID 39873807, 2025). "The results revealed that unlike IFN-γ, IL-4, IL-5, IL-13, ALOX15, CST1, POSTN, and CCL26 were significantly elevated in patients with eosinophilia greater than 5%." (PMID 40978168, 2025). "IL-4, IL-5, IL-13, ALOX15, CST1, POSTN, and CCL26 were significantly elevated in patients who had eosinophilia higher than 5%, but not IFN-γ." (PMID 40978168, 2025). "Moreover, since EGPA and GPA with elevated blood eosinophilia share some clinical traits, diagnostic confusion may lead to inappropriate therapy, e.g., some “eosinophilic” GPA patients may benefit from anti-IL-5 strategy, usually not recommended in AVV other than EGPA." (PMID 38699219, 2024). "IL-5 levels are elevated in both serum and BAL, but do not necessarily correlate with the degree of eosinophilia in lungs." (PMID 38711783, 2024). "Our observations of increased Th1 (TNFα) and Th2 (IL-5, IL-33) cytokine concentrations in the BALF of dams fed a high fat diet, without any neutrophilia or eosinophilia suggest that these mice are ‘poised’ to react to further allergenic or viral exposure." (PMID 30700289, 2019). "In sputum, absolute IL-5 + HPC counts, but not percentages, were elevated in COPD patients with sputum eosinophilia (16.83 ± 14.65 × 102 /gram of sputum vs 0.19 ± 0.07 × 102 /gram of sputum; p < 0.01)." (PMID 29859068, 2018). "Neutralization of IL5 with antibodies or genetic deletion of IL5 significantly reduced the number of cutaneous and circulating eosinophils in Sharpincpdm mice, but did not alter the inflammatory phenotype suggesting that eosinophilia may be a secondary response rather than the initiating mechanism." (PMID 22452937, 2012). "Recent models of chronic airway allergen exposure demonstrated that the lack of IL-5 did not affect collagen deposition or AHR, while inhibiting BAL eosinophilia completely." (PMID 18253511, 2008). "The intermediate levels of IL-5 and TNF-α observed in RA subjects suggest that in some individuals elevated local concentrations of these cytokines remain, although in the absence of substantial eosinophilia." (PMID 23043798, 2012). "Since no major CCL11 or IL-5 signature was observed in TIV-vaccinated NC99-challenged mice, we may be observing CCL5-mediated recruitment of eosinophils instead of canonical Type 2 cytokine-driven eosinophilia." (PMID 37600776, 2023). "Alternatively, IL-5 may be working as an independent chemotactic factor by which both IL-5R ligation and CCR-3 ligation are nonredundant signals combining to mediate peritoneal tissue eosinophilia in response to filarial parasitism." (PMID 32571840, 2020). "In light of these findings, we further demonstrated that combined IL-2/JES6-1 immunocomplex and anti-IL-5 mAb treatment was most effective at ameliorating DSS-induced colitis compared to either treatment alone and that this regimen allowed for Foxp3+ Treg expansion without concomitant eosinophilia." (PMID 30930900, 2019).
eosinophilia (continued). "In light of these findings, we observed that combined IL-2/JES6-1 and anti-IL-5 mAb treatment was most effective at ameliorating DSS-induced colitis compared to either treatment alone and that this regimen allowed for Foxp3+ Treg expansion without concomitant eosinophilia." (PMID 30930900, 2019). "However, the use of mepolizumab, an anti-IL-5 antibody, in the first clinical trial did not result in a decrease in SCORAD indices and did not significantly affect the pruritus score and the TARC severity marker compared to the control, despite a reduction in eosinophilia." (PMID 38672221, 2024).
Allergy (331 papers, 2002 to 2026). An allergy is an immune response or reaction to substances that are usually not harmful. "IL-5 is produced by Th2 cells, mast cells, airway smooth muscle, and epithelial cells, and it is associated with increased eosinophils during allergies or parasitic infections." (PMID 40958130, 2025). "In vivo, the BsAb TAVO101 × IL4R-dupi reduced all hallmark features of allergic disease, including IgE production, IL-5 and CCL17 levels, eosinophilic infiltration, and mucus hypersecretion." (PMID 41294800, 2025). "Th2 cells respond to antigens from the breast, which in turn triggers IgE production and activation of allergy‐associated immune cells, which in turn are able to promote a pro‐inflammatory cytokine cascade, producing IL‐4 and IL‐5." (PMID 39619969, 2024). "Th2 cytokines, such as IL-4, IL-5 and IL-13, have a number of effects associated with allergy, including IgE class-switching by B cells, eosinophil activation and recruitment, and mucus production." (PMID 40115160, 2024). "In our study, patients with Chagas cardiomyopathy presented a higher concentration of the cytokine IL-5, which stimulates B cell growth, increases immunoglobulin IgA, and has long been causally associated with several allergic diseases." (PMID 38133693, 2023). "The IL-13 gene is located on the 5q31 chromosome, which also encodes other factors involved in allergy mechanisms such as IgE, IL-4, IL-3, and IL-5." (PMID 35629280, 2022). "IL-5, IL-9, IL-10, IL-23, and IL-27 are also related to the Th2 response (T-cell response associated with allergies, progressive systemic sclerosis, and autoimmune disorders)." (PMID 36439158, 2022). "In the Th2 type inflammation/allergy, the Th2 cytokines, including IL-5, which is implicated in the induction and proliferation of eosinophils, play a critical role." (PMID 35637792, 2022). "Th2 response up-regulates the expression of IL-4, IL-5, and IL-13, which are essential for allergic diseases caused by the pathogenic infection." (PMID 36119076, 2022). "Many similarities exist between IgG4-RD and allergic diseases, such as the increase of eosinophil counts, IgE, IgG4, and Th2 associated cytokines (IL-4, IL-5, and IL-13)." (PMID 35432312, 2022). "On the one hand, IL-25 activates type 2 immunity via the relevant cytokines, including IL-4, IL-5, and IL-13, which are associated with the development of pathogenic infection-related allergic diseases." (PMID 36119076, 2022). "Expression of allergy-associated cytokine genes, including Il4, Il5, Il9, Il13, and Il21, was higher in Nr4a-TKO cells, even when compared with Foxp3-KO cells." (PMID 33665581, 2021). "Similar to allergies, helminth infections induce a Th2 immune response associated with cytokines such as interleukin (IL)-4, IL-5, IL-9, IL-13, and increased levels of eosinophils, basophils, mast cells and circulating IgE Abs." (PMID 32268573, 2020). "Analysis of the polarization of cytokine production revealed that responses were dominated by IL-5 (63.1%), suggesting that the detected T cell reactivity conforms to the classical functional phenotype of allergy-associated T cells." (PMID 29755469, 2018). "We aimed to study the expression of the Th2 cytokine (IL-4, IL-5, and IL-13) genes, which are implicated in allergic reactions, and changes in the actual secretion of the cytokines." (PMID 29772010, 2018). "The prevention of allergy is known to be associated with the downregulations of IL‐4, IL‐5, IL‐13 and IL‐10." (PMID 28165193, 2017). "The protein-coding genes listed were closely linked to allergy and associated with lncRNAs; moreover, some of them such as Il4, Il5, and Il13 were regulated by iPSC-MSC treatment, and therefore these lncRNAs were also associated with iPSC-MSC immunomodulation." (PMID 28057064, 2017).